PABIR1 (PP2A Aalpha (PPP2R1A) and B55A (PPP2R2A) interacting phosphatase regulator 1)
Description:
Acts as an inhibitor of serine/threonine-protein phosphatase 2A (PP2A) activity. Inhibits PP2A activity by blocking the substrate binding site on PPP2R2A and the active site of PPP2CA. Potentiates ubiquitin-mediated proteasomal degradation of serine/threonine-protein phosphatase 2A catalytic subunit alpha (PPP2CA). Inhibits PP2A-mediated dephosphorylation of WEE1, promoting ubiquitin-mediated proteolysis of WEE1, thereby releasing G2/M checkpoint.
Synonyms: C9orf42; FAM122A; MGC17347
Tractability: PROTAC: UniProt records ubiquitination sites on it.
Gene: Protein-coding gene on chromosome 9 (68,780,065 to 68,785,566, forward strand). Ensembl gene ENSG00000187866.
Subcellular location: Nucleus; Cytoplasm
Subcellular location (Human Protein Atlas): Nuclear bodies; Nucleoplasm
Gene Ontology:
Molecular function: protein binding; protein phosphatase 2A binding; protein phosphatase inhibitor activity; protein serine/threonine phosphatase inhibitor activity
Biological process: mitotic G2/M transition checkpoint; positive regulation of cell growth; positive regulation of proteasomal ubiquitin-dependent protein catabolic process
Cellular component: cytoplasm; nuclear body; nucleoplasm; nucleus
Genetic constraint (gnomAD): Loss-of-function variants: 2 observed, 15.48 expected, observed/expected ratio (o/e) 0.13, 90% interval 0.052 to 0.41. The upper end of that interval is the gene's LOEUF score, 0.41, which puts it in group 1 of 6, group 1 being the genes least tolerant of losing a copy. Missense variants: 294 observed, 381.74 expected, observed/expected ratio (o/e) 0.77, 90% interval 0.7 to 0.85. Synonymous variants: 163 observed, 154.78 expected, observed/expected ratio (o/e) 1.05, 90% interval 0.93 to 1.2.
Homologues: Orthologues: pig PABIR1 (99% identical), guinea pig PABIR1 (98% identical), rabbit PABIR1 (98% identical), mouse Pabir1 (97% identical), rat Pabir1 (97% identical), zebrafish pabir2 (64% identical), tropical clawed frog pabir2 (57% identical), Drosophila melanogaster CG4497 (34% identical), Caenorhabditis elegans F46H5.2 (29% identical). Paralogues in human: PABIR2 (65% identical), PABIR3 (54% identical).
Diseases named in the same sentence as PABIR1 in open-access papers:
PABIR1 is named in the same sentence as 5 diseases in open-access papers, as found by Europe PMC text mining. Sharing a sentence is not in itself a finding about the gene and the disease.
PABIR1 shares sentences with these, for which no sentence is quoted: lung carcinoma (2 papers); acute T cell leukemia (1); cancer (1); chronic kidney disease (1); tumour (1).